NCAPG2 (non-SMC condensin II complex subunit G2)
Diseases named in the same sentence as NCAPG2 in open-access papers (continued):
Sharing a sentence is not in itself a finding about the gene and the disease.
tumor (22 papers, 2012 to 2025). "NCAPG2 was identified to be overexpressed in almost every tumor and exhibited significant prognostic and diagnostic efficacy." (PMID 39062863, 2024). "NCAPG2 was identified to be overexpressed in almost every tumor and to exhibit significant prognostic and diagnostic efficacy." (PMID 36776838, 2023). "We found that high expression of NCAPG2 was associated with higher tumor grades, IDH mutation status, 1p/19q chromosome co-deletion, and age." (PMID 35898895, 2022). "We found that high expression of NCAPG2 was associated with higher tumor grades, histological type, IDH mutation status, 1p/19q chromosome co-deletion, and primary therapy outcome." (PMID 35898895, 2022). "Results demonstrated that NCAPG2 expression, tumor grades, IDH mutation status, and 1p/19q chromosome co-deletion, and age were independent risk factors for overall survival." (PMID 35898895, 2022). "NCAPG2 promotes tumor proliferation by regulating the G2/M phase and is associated with poor prognosis in LUAD." (PMID 36139554, 2022). "Meanwhile, increased expression of NCAPG2 was associated with poor clinical characteristics, including higher tumor grades, histological type, IDH mutation status, 1p/19q chromosome co-deletion, and primary therapy outcome." (PMID 35898895, 2022). "Furthermore, NCAPG2 has been linked to the modulation of immune responses, suggesting its potential role in the tumor microenvironment." (PMID 40447854, 2025). "The regulation of NCAPG2 by RPL35A may represent a critical mechanism underlying RPL35A‐driven tumor progression." (PMID 40552444, 2025). "Moreover, in order to deeply analyze the association between NCAPG2 and tumor immunity, the study evaluated the relevance of its expression to immune checkpoint-related genes and immune cell infiltration scores." (PMID 36776838, 2023). "We calculated the correlation between gene expression and pathway scores and found that NCAPG2 expression was significantly associated with angiogenesis, apoptosis, cellular response to hypoxia, DNA repair, tumor proliferation, DNA replication, glycolysis, EMT, ferroptosis, G2M checkpoint in PC." (PMID 36776838, 2023). "And high NCAPG2 expression was associated with advanced clinical tumor stage." (PMID 36059662, 2022). "Furthermore, the correlations between NCAPG2 and various immune parameters, such as immune cell infiltration, immune checkpoint genes, tumor mutational burden (TMB) and microsatellite instability (MSI), hint at its potential in guiding immunotherapeutic strategies." (PMID 40552444, 2025). "Furthermore, we utilized the Cox regression model for multivariate analysis; the results demonstrated that NCAPG2 expression, tumor grades, IDH mutation status, and primary therapy outcome may be an independent risk factor for overall survival." (PMID 35898895, 2022). "We compared the mRNA expression levels of NCAPG2 from tumor tissues with the adjacent non-tumor tissues." (PMID 40447854, 2025). "NCAPG2, a subunit of the chromosomal condensin II complex, is increasingly recognized for its role in tumor evolution." (PMID 40447854, 2025). "Parallel observations in the circRNA combination cohort revealed sustained downregulation of key classical oncogenes (PIK3CA) and novel tumor-associated genes (ANXA2, KIF2A, NCAPG2, PAIP1)." (PMID 40426998, 2025). "The findings revealed a significant increase in the expression of NCAPG2 across a range of tumor tissues." (PMID 40447854, 2025). "Histologic examination for tumors indicated that silencing NCAPG2 apparently impaired the tumor growth." (PMID 38166947, 2024). "The sphere-forming ability of both cell lines declined significantly following NCAPG2 knockdown, while NCAPG2 upregulation facilitated more tumor spheres." (PMID 38166947, 2024). "NCAPG2 was overexpressed in many tumor types, and this overexpression is related to poor clinical stages and prognosis." (PMID 37501987, 2023).
tumor (continued). "We conducted a comprehensive study to analyze the correlation between specific genetic alterations in NCAPG2 and their impact on clinical prognosis across multiple tumor types." (PMID 37501987, 2023). "Further, in the invasion assay, it was observed that NCAPG2 knockdown resulted in a statistically significant reduction in the amount of tumor cells travelling through the Matrigel." (PMID 36776838, 2023). "We further integrated QUANTISEQ, EPIC, and TIMER, three well-established algorithms designed to assess cross-tumor immune scoring, to assess the correlation between NCAPG2 expression and immune cell levels, building on the analysis of immune infiltration." (PMID 36776838, 2023). "For example, NCAPG2 regulates the G2/M phase to facilitate tumor proliferation, and its expression has been correlated with an unfavorable prognosis in lung cancer." (PMID 37501987, 2023). "We further examined the correlation between NCAPG2 and immune cell infiltration, microsatellite instability (MSI), tumor mutational burden (TMB), immune-related genes, and immune checkpoint gene in different TMEs." (PMID 37501987, 2023). "The CCLE database revealed significantly elevated expression of NCAPG2 in 38 tumor cell lines, with salivary gland, lung, and hematopoietic and lymphoid cell lines showing the highest levels of NCAPG2 enrichment." (PMID 37501987, 2023). "The results are presented in, where distinct tumor stemness scores were significantly correlated with NCAPG2 in 15 tumors, with a significant positive correlation in 14 of these." (PMID 36776838, 2023). "In the future, we will pay more attention to the function of NCAPG2 in tumor progression and tumor microenvironment regulation of LGG." (PMID 35898895, 2022). "The tumor sphere-formation assay indicated that the diameter of the spheres from the erlotinib resistance cells with NCAPG2 knockdown was significantly smaller than that of the controls." (PMID 36139554, 2022). "In summary, our study confirmed the potential role of NCAPG2 in regulating tumor progression and its potential application in the diagnosis and prognostic evaluation of LUAD." (PMID 35664767, 2022). "Many studies have shown that NCAPG2 is highly expressed in tumors and involved in tumor proliferation, metastasis, and invasion." (PMID 36139554, 2022). "We used the NCAPG2 expression and tumor grades to construct a prognostic nomogram, and a calibration curve was drawn to test the efficiency of the nomogram." (PMID 35898895, 2022). "The results showed that NCAPG2 expression increased with the tumor stage, lymph node invasion, and distant metastasis." (PMID 36139554, 2022). "The expression level of NCAPG2 protein in lung AD tissues were significantly higher than those in corresponding non‐tumour tissues (P = 0.0001)." (PMID 27862966, 2017). "In this study, we found that NCAPG2 expression was significantly increased in NSCLC tissues compared to adjacent normal lung tissues, and was closely associated with tumour progression and poor prognosis in lung AD patients." (PMID 27862966, 2017). "Notably, the silencing of NCAPG2 effectively reversed the tumor‐promoting effects induced by RPL35A in HCC cells, underscoring the regulatory association between RPL35A and NCAPG2." (PMID 40552444, 2025). "Furthermore, it has been observed that Brachyury, by promoting the transcription of NCAPG2, plays a tumor‐promoting role in HCC." (PMID 40552444, 2025). "This suggests that NCAPG2 methylation might hinder the migration of immune cells into tumor microenvironment." (PMID 40447854, 2025). "In addition, the results show that CKS2, PCNA, CHEK1, and NCAPG2 are also involved in the regulation of tumor DNA replication and mismatch repair." (PMID 38937855, 2024). "Moreover, our findings from the subcutaneous and orthotopic xenograft tumor models suggested that NCAPG2 knockdown was sufficient to significantly reduce tumor size." (PMID 38166947, 2024).
tumor (continued). "A series of functional assays revealed that NCAPG2 could promote PCa cell proliferation, migration, and invasion, thus further strengthening the essential role for condensin complex components in tumor progression and cell cycle regulation." (PMID 38166947, 2024). "IHC analysis revealed that silencing circ0001955 could decrease the expression of NCAPG2 in tumor tissues." (PMID 37248471, 2023). "Also, NCAPG2 exhibited remarkable correlation with both immune cell infiltration and immune checkpoint genes, hinting that the potential as a target for tumor immunotherapy." (PMID 36776838, 2023). "We infer that NCAPG2, as a pan-oncogene, may be able to enhance its malignancy by forming positive feedback with certain immune checkpoint genes, enabling tumor cells to be immune surveillance free." (PMID 36776838, 2023). "Therefore, the study aimed to comprehensively elucidate the immune characteristics and prognostic of NCAPG2 in tumor microenvironments (TMEs)." (PMID 37501987, 2023). "Following this, the transwell and invasion assay was applied to test the migration and invasion ability of selected cells, and the transwell assay proved that the migration ability of tumor cells was significantly reduced when NCAPG2 was down-regulated in PANC1, which was also evident in MIAPaCa-2." (PMID 36776838, 2023). "More recently, NCAPG2 has emerged as an intrinsically essential participant of the condensin II complex involved in the process of chromosome cohesion and stabilization in mitosis, and its position in particular tumours is now being highlighted." (PMID 36776838, 2023). "This suggested that NCAPG2 might play a pro-tumor role through the mTORC1 signaling pathway, DNA repair, and MYC targets." (PMID 36139554, 2022). "Then, expression levels of NCAPG2 in the subcutaneous tumor were detected by Western blot analyses." (PMID 36059662, 2022). "Based on previous research, we conjecture that tumor immune escape mediated by NCAPG2 and EIF2S3 may be involved in LUAD erlotinib resistance and stemness." (PMID 36139554, 2022). "Furthermore, we will perform more in vivo and vitro experiments to explore the function and the potential molecular mechanisms of NCAPG2 in tumor progression and tumor microenvironment regulation of LGG." (PMID 35898895, 2022). "Moreover, RPL35A overexpression increased NCAPG2 levels, promoting tumor progression." (PMID 40552444, 2025). "Notably, NCAPG2 methylation showed a positive correlation with TNFSF4 (r = 0.347, p = 0.0386).Therefore, NCAPG2 may linked to regulate tumor immunity." (PMID 40447854, 2025). "Cell proliferation, wound healing, transwell, flow cytometry, cell cycle, tumor sphere formation, immunofluorescence (IF), co-immunoprecipitation (co-IP), and chromatin immunoprecipitation (ChIP) assays were conducted to further elucidate the molecular mechanism of NCAPG2 in PCa." (PMID 38166947, 2024). "In this study, our main objective was to elucidate the role of NCAPG2 in CHOL, particularly its expression levels and their correlation with tumor immune response and methylation patterns." (PMID 40447854, 2025). "Tumor purity is also thought to impinge on the efficacy of ICI treatment, and NCAPG2 displayed a significant correlation with purity, which was more prominent in GBM, SARC, SKCM, ACC, LUSC, STAD and others, with some similarity to TMB and MSI." (PMID 36776838, 2023). "First, although we explored the correlation between NCAPG2 and immune infiltration in LUAD patients, there is a lack of experiments to validate the function of NCAPG2 in the tumor microenvironment regulation of LUAD." (PMID 35664767, 2022). "To determine the effect of NCAPG2 on the stemness of LUAD, we performed a tumor sphere-formation assay and SP detection by flow cytometry." (PMID 36139554, 2022). "Furthermore, IHC analysis of subcutaneous tumors indicated that NCAPG2 knockdown led to reduction in the level of c-MYC, following tumor shrinkage in vivo (Welch’s t-test P < 0.01)." (PMID 38166947, 2024).
tumor (continued). "Patients with residual tumors post-surgery also presented with NCAPG2 overexpression (R0: no residual tumor; R1: microscopic residual tumor; R2: macroscopic residual tumor) (Wilcoxon test, P < 0.05)." (PMID 38166947, 2024). "Moreover, we found that circ0001955 promoted tumor proliferation and invasion in CSCC by modulating the expression of NCAPG2." (PMID 37248471, 2023). "The results indicated that NCAPG2 was significantly correlated with the level of B cells, CD8+ T cells, CD4+ T cells, macrophages, neutrophils, and dendritic cells, and negatively correlated with tumor purity." (PMID 35898895, 2022). "Furthermore, we found that NCAPG2 was significantly correlated with the level of B cells, CD8+ T cells, CD4+ T cells, macrophages, neutrophils and dendritic cells, and was negatively correlated with tumor purity." (PMID 35898895, 2022). "Furthermore, comparing NCAPG2 with immunomodulatory-related genes, including histocompatibility complex (MHC), chemokine and chemokine receptor genes, it was found that the three gene families were strongly correlated with NCAPG2 expression levels in most tumor types." (PMID 36776838, 2023).
infection (1 paper, 2025). The state of being infected such as from the introduction of a foreign agent such as serum, vaccine, antigenic substance or organism. "Conversely, overexpressing RPL35A markedly elevated NCAPG2 levels in cells, which was reversed upon co‐infection with shNCAPG2." (PMID 40552444, 2025).
lung (1 paper, 2017). "In the present study, transfection with si‐NCAPG2 in lung AD cell caused the accumulation of the CKIs p21 and p27, and reduction in Cdc2 and Cyclin B expression, leading to G2/M phase arrest." (PMID 27862966, 2017). "It is plausible that alterations in cell cycle‐associated proteins may lead to the arrest of G2/M phase in lung AD cell cells with knockdown of NCAPG2." (PMID 27862966, 2017).
NCAPG2 also shares sentences with these, for which no sentence is quoted: colon cancer (3 papers); microcephaly (3); epithelial ovarian cancer (2); prostate carcinoma (2); adrenocortical carcinoma (1); astrocytoma (1); Behcet’s syndrome (1); dedifferentiated liposarcoma (1); epidermolytic hyperkeratosis (1); fibrosarcoma (1); lung squamous cell carcinoma (1); Malignant Fibrous Histiocytoma (1); mesothelioma (1); myxofibrosarcoma (1); nasal polyps (1); neurodevelopmental disorder (1); oligoastrocytoma (1); oligodendroglioma (1); ovarian cancer (1); pancreatic adenocarcinoma (1); pleomorphic liposarcoma (1); round cell liposarcoma (1); skin cutaneous melanoma (1); synovial sarcoma (1); uterine corpus endometrial carcinoma (1).